MUC5AC (mucin 5AC, oligomeric mucus/gel-forming)
Diseases named in the same sentence as MUC5AC in open-access papers (continued):
Sharing a sentence is not in itself a finding about the gene and the disease.
colorectal cancer (33 papers, 2006 to 2025). A primary or metastatic malignant neoplasm that affects the colon or rectum. "Immunohistochemical features distinguishing MC from conventional colorectal carcinoma include prominent positivity for MUC5AC, considered a hallmark of this histological subtype." (PMID 41458856, 2025). "In summary, the results of our study show that elevated MUC5AC expression is independently linked to proximal location and dMMR in colorectal cancers." (PMID 33373033, 2021). "MUC5AC expression is associated with tumorigenesis in colorectal cancer via a serrated neoplasia pathway." (PMID 34503106, 2021). "The results of our study show a strong association of MUC5AC expression with proximal and dMMR colorectal cancers." (PMID 33373033, 2021). "MUC5AC hypomethylation was an independently predictor of microsatellite instability associated with colorectal cancer." (PMID 28938681, 2017). "In colorectal carcinoma patients we demonstrate the presence of serum MUC5AC antibodies is associated with decreased survival." (PMID 16409634, 2006). "MUC5AC positivity was significantly associated with colorectal cancer localization." (PMID 33373033, 2021). "Since MSI is linked to favorable prognosis in colorectal cancer, a favorable disease course could be expected in MUC5AC-positive cancers." (PMID 33373033, 2021). "High expression of MUC5AC was associated with favorable outcome in colorectal cancer, notably in intermediate stages II and III, and absence of MUC5AC expression might be a prognostic factor for more aggressive colorectal carcinoma." (PMID 28938681, 2017). "In a related study on colorectal cancer, phage display technology was used to select disulfide-restricted heptapeptides that bind human gastric mucin MUC5AC." (PMID 41019528, 2025). "The potential use of MUC5AC contrast agents in diagnosis, early detection of colorectal cancer recurrence after treatment, and in mechanistic studies involving MUC5AC has been highlighted by this study." (PMID 37601380, 2023). "They found that while MUC5AC can help distinguish colorectal cancer from PMOC, it cannot contribute to the differential diagnosis of PMOC and pancreatic mucinous carcinoma." (PMID 37664708, 2023). "MUC5AC has been shown to be expressed in ~50% of colorectal cancers (CRCs), while MUC4 overexpression is only seen in ~25% of CRCs." (PMID 37185743, 2023). "(F) Disease-free survival (DFS) of colorectal cancer patients with high (n = 73) or low (n = 153) MUC5AC levels (Jorissen cohort)." (PMID 35131032, 2022). "A total of 23 studies have earlier analyzed MUC5AC expression in colorectal cancer and described MUC5AC expression to occur in 0–95% analyzing 22–649 cancers." (PMID 33373033, 2021). "In colorectal cancer, positive MUC5AC staining was seen in 261 (15.7%) of 1667 analyzable tumor spots." (PMID 33373033, 2021). "In the colon, MUC5AC is expressed in scattered normal epithelial cells but can be abundant in colorectal cancers." (PMID 33373033, 2021). "The 11 studies analyzing the prognostic relevance of MUC5AC expression in colorectal cancer in cohorts of 35–649 patients have found divergent results." (PMID 33373033, 2021). "As the expression of MUC5AC in colorectal cancer tissues is abnormal, what is the humoral immune response to this abnormal protein expression?" (PMID 32695780, 2020). "Other mucin changes in colorectal cancer have been reported for de novo expression of MUC5AC and MUC 20 overexpression." (PMID 28012131, 2017).
colorectal cancer (continued). "The current data collectively supports the notion that higher expression of MUC2 and MUC5AC confers genetic and molecular features on colorectal carcinomas that incur adverse consequences in relation to treatment response and clinical outcome." (PMID 26436698, 2015). "In the aggressive type of sporadic colorectal carcinomas, several reports have shown the importance of MUC5AC expression." (PMID 23691335, 2013). "MUC5AC antibodies were detected in 6 of 22 (27.3%) healthy subjects, 9 of 20 (45%) polyp patients, 18 of 30 (60%) patients with colorectal cancer." (PMID 16409634, 2006). "Serum mean MUC5AC antibody levels were higher in colorectal carcinoma patients when compared with polyp patients (p = 0.049) and a control population (p = 0.011)." (PMID 16409634, 2006). "A second aim was to determine the relationship of MUC5AC antibody with the prognosis of colorectal carcinoma." (PMID 16409634, 2006). "In the present study we have demonstrated the presence of antibodies to MUC5AC epitopes in sera of healthy individuals, patients with polyps and colorectal carcinoma." (PMID 16409634, 2006). "MUC5AC antibody positive individuals were significantly higher in colorectal carcinoma 60% than in healthy controls 27.3% (p = 0.019)." (PMID 16409634, 2006). "In order to determine the positive cut off level of serum MUC5AC Ab, a ROC (receiving operating characterizing) curve was constructed between the normal and pathologic (polyps and colorectal carcinoma patients) groups." (PMID 16409634, 2006). "The present study investigates the incidence of naturally occurring MUC5AC antibodies in the sera of normal individuals, patients with colonic polyps and patients with advanced colorectal carcinoma." (PMID 16409634, 2006). "Fluorescent antibodies to mucin5AC (MUC5AC), a glycoprotein upregulated in adenomas and colorectal cancer, could improve screening colonoscopy polyp detection rate." (PMID 37185743, 2023). "We thus analyzed the relationship between MUC5AC expression and features of tumor aggressiveness (pT and pN) in all cancers and in the subgroup of pMMR and dMMR cancers in a cohort of 1812 colorectal cancers by immunohistochemistry (IHC) in a tissue microarray (TMA) format." (PMID 33373033, 2021). "However, our multivariate analysis revealed that tumor location and dMMR independently enhanced the likelihood for detectable MUC5AC expression in colorectal cancer." (PMID 33373033, 2021). "MUC5AC expression was found in 16% of colorectal cancers in our study." (PMID 33373033, 2021). "MUC5AC expression was found in 261 (15.7%) of 1,667 analyzable colorectal cancers." (PMID 33373033, 2021). "Mucin 5AC (MUC5AC) is a biomarker of potential interest in colorectal cancer." (PMID 33373033, 2021). "Building on our previous results, we could suggest that the serum MUC5AC antibody level would be low in colorectal carcinoma patients with favorable outcome for these tumors would be expressing more MUC5AC." (PMID 16409634, 2006). "In our previous study, we reported 34.1% of colorectal carcinomas expressed MUC5AC." (PMID 16409634, 2006). "A significant IgG antibody response to MUC5AC in colorectal carcinoma patients may be indicative of a CD4 helper T cell response." (PMID 16409634, 2006). "It has been hypothesized that aberrant expression of MUC5AC in colorectal carcinoma tissues increased the overall survival of patients with colorectal carcinoma." (PMID 16409634, 2006). "Decreased survival in colorectal carcinoma patients with MUC5AC antibody positivity may be due to a decrease in the MUC5AC expression in tumor tissues of surviving carcinoma patients." (PMID 16409634, 2006). "In addition to MUC2, the abnormal expression of MUC5AC is also observed in colorectal cancer." (PMID 40699805, 2025).
colorectal cancer (continued). "In the study, we used the same immunohistochemical antibody and cutoff criteria and demonstrated that CLDN18 expression was seen in 27% of colitis-associated colorectal carcinomas with an association of MUC5AC expression, while without significant association with MUC6 status." (PMID 39164422, 2025). "However, the absence of associations between MUC5AC expression and pT as well as pN argues against a clinically relevant role of MUC5AC expression for driving aggressiveness of human colorectal cancer cells." (PMID 33373033, 2021). "However, multiple studies have provided evidence that MUC5AC expression may drive cancer aggressiveness in colorectal cancer cell lines and xenograft models." (PMID 33373033, 2021). "However, in another study, there was de novo expression of MUC5AC in 23/36 colorectal carcinomas." (PMID 16409634, 2006). "Mammotome biopsy of the breast lesion revealed histopathological features consistent with colorectal carcinoma metastasis, including partial CK20 positivity, CK7 negativity, CDX2 negativity, and MUC5AC positivity." (PMID 41458856, 2025). "The MUC profile in the FCCTX subset was more akin to that of unselected colorectal cancers with MUC2 expression reported in 40–54%, MUC5AC in 6–10% and MUC6 in 4%." (PMID 28824332, 2017). "In colorectal carcinoma, these rates are MUC1, 24–32%; MUC2, 38%; MUC3, 74%; MUC4, 94%; MUC5AC, 34–50%; MUC6, 39%; and MUC16, 64%." (PMID 25551773, 2014). "MUC5AC is highly expressed in the upper GI tract and is not expressed in the normal colon, however, abnormal expression is observed in colorectal cancer." (PMID 29942513, 2018). "We investigated the core protein-expression levels of MUC2, MUC5AC, MUC6, and CD10 because altered expressions of these proteins may be significantly correlated with the biological behavior of colorectal carcinoma and, possibly its prognosis." (PMID 30458818, 2018). "In our previous study, we demonstrated that colorectal carcinoma patients with MUC5AC negative tumors had poor clinicopathological parameters and showed worse survival than patients having MUC5AC positive tumors." (PMID 16409634, 2006). "The authors examined the impact of reduced (shRNA-mediated) or absent (CRISPR/Cas9-mediated) MUC5AC expression on cell proliferation, anchorage independent cell growth, cell migration, and cell invasion in two endogenous MUC5AC expressing colorectal cancer cell lines." (PMID 33373033, 2021). "Moreover, MUC5AC, a normal component of gastric mucus which is usually absent from the colon, was shown to be expressed de novo in colorectal cancer." (PMID 33013869, 2020). "We suggested that the absence of MUC5AC expression in colorectal carcinomas might be a negative prognostic factor." (PMID 16409634, 2006). "Interestingly, the introduction of the mutant GNAS into a colorectal cancer cell line markedly induced MUC2 and MUC5AC expression, but did not promote cell growth either in vitro or in vivo." (PMID 24312577, 2013).
chronic obstructive pulmonary disease (28 papers, 2011 to 2025). A chronic and progressive lung disorder characterized by the loss of elasticity of the bronchial tree and the air sacs, destruction of the air sacs wall, thickening of the bronchial wall, and mucous accumulation in the bronchial tree. "MUC5AC expression is upregulated in chronic obstructive airway diseases such as COPD, CF and asthma, and this contributes to mucus hypersecretion in patients with these diseases." (PMID 34072295, 2021). "MUC5B is essential for cilia motility, while MUC5AC is more responsive to environmental or infectious factors, and elevated concentrations of MUC5AC may contribute to the development of chronic obstructive pulmonary disease (COPD)." (PMID 37894512, 2023). "The potential role and regulatory mechanisms of MUC5AC in chronic obstructive pulmonary disease remain unclear." (PMID 35518345, 2022). "Tobacco smoking induces MUC5AC expression and MUC5AC expression is elevated in the airways of patients with chronic obstructive pulmonary disease (COPD)." (PMID 39137525, 2024). "Whereas decreased AQP5 expression and overproduction of MUC5AC have been reported in airways of patients with chronic obstructive pulmonary disease (COPD)." (PMID 29112967, 2017). "Extracellular ATP was induced by dsRNA and released via pannexin channel in chronic obstructive pulmonary disease (COPD), which resulted in the release of MUC5AC in an autocrine manner, mainly via P2Y2 receptor." (PMID 28938681, 2017). "In chronic obstructive pulmonary disease (COPD), a multicenter observational study reported higher sputum levels of both mucins than in healthy controls, with a predominant increase in MUC5AC." (PMID 41561092, 2025). "Goblet cell metaplasia and MUC5AC expression are increased under pathological conditions such as chronic rhinosinusitis or chronic obstructive pulmonary disease (COPD); in addition, cigarette smoke enhanced the pathological response, which was mainly mediated by the EGFR pathway." (PMID 38892239, 2024). "We identified elevations in airway mucin 5AC (MUC5AC) and MUC5B concentrations during spontaneous and experimentally induced chronic obstructive pulmonary disease (COPD) exacerbations." (PMID 35239513, 2022). "Different subtypes of mucin have differing properties and predominate in different disease states (MUC5AC dominates in asthma; MUC5B dominates in chronic obstructive pulmonary disease (COPD)." (PMID 35399263, 2022). "Elevated levels of MUC5AC and MUC5B have been reported in asthma patients, and elevated MUC5B levels have been observed in patients with chronic obstructive pulmonary disease (COPD)." (PMID 31514468, 2019). "Highly significant DEGs including CYP1A1, HHIP (hedgehog interacting protein), MUC5AC, and CYP2A6 might be related to the pathophysiology of chronic obstructive pulmonary disease." (PMID 38137330, 2023). "The increased expression of MUC5AC has been reported in the bronchiolar epithelium and submucosal glands, whose tendency is inversely related to forced expiratory volume in 1 s percent predicted (FEV1% pred) against chronic obstructive pulmonary disease (COPD) in clinical practice." (PMID 36339607, 2022). "In human pathological conditions, such as asthma, chronic obstructive pulmonary disease (COPD) and cystic fibrosis, mucin expression is altered with an increase in the amounts of both MUC5B and MUC5AC." (PMID 21602926, 2011).
cystic fibrosis (26 papers, 2011 to 2025). Autosomal recessive disorder caused by pathogenic variants in the CFTR gene (cystic fibrosis transmembrane conductance regulator), which encodes a chloride and bicarbonate channel expressed in epithelial cells, and follow the diagnosis criteria. "In addition to Muc5ac, Muc2 is also associated with inflammatory airway diseases such as chronic bronchitis, and cystic fibrosis." (PMID 26084512, 2015). "The impact of mucus rheology is particularly significant in conditions such as cystic fibrosis, where the accumulation of thick, cross-linked MUC5B and MUC5AC impairs mucociliary clearance and exacerbates infection and inflammation." (PMID 41158440, 2025). "For instance, the major gel-forming mucins MUC5B and MUC5AC in the sputum of cystic fibrosis patients display a distinctive glycosylation pattern, characterized by reduced sulfation, increased sialylation, and decreased fucosylation." (PMID 41257290, 2025). "MUC5B is produced at baseline in the lungs and MUC5AC is upregulated in response to a challenge, an infection, as well as a chronic lung condition like cystic fibrosis." (PMID 36117114, 2023). "We found that PEGylation does not make the differencewhen the mucus barrier properties are dominated by pathology-associatedproteins, such as the gel-forming mucins MUC5AC and MUC5B (i.e., sputumfrom cystic fibrosis patients)." (PMID 35107987, 2022). "Moreover, inhibiting TRP cation channel subfamily M member 4 (TRPM4) protein activity in cystic fibrosis cell lines abolished MUC5AC secretion." (PMID 39958344, 2025). "Mucus accumulation and airway mucus plugging are part of cystic fibrosis pathophysiology and the total mucus concentration as well as the staining intensity for MUC5AC and MUC5B were elevated in bronchioalveolar lavage fluid from children with cystic fibrosis compared to age matched controls." (PMID 36927357, 2023). "However, other test materials were not able to promote any changes in Muc5AC protein expression, including CFTRinh-172, experimentally used to mimic the inflammatory profile found in cystic fibrosis, a disease marked by mucus hyperproduction." (PMID 40061084, 2025). "MUC5AC and MUC5B are involved in the pathogenesis of respiratory infectious diseases, such as cystic fibrosis and chronic obstructive pulmonary disease, and contribute considerably to amplification of inflammation and tissue injury." (PMID 22768318, 2012).